SYT7 (synaptotagmin 7)
Description:
Ca(2+) sensor involved in Ca(2+)-dependent exocytosis of secretory and synaptic vesicles through Ca(2+) and phospholipid binding to the C2 domain (By similarity). Ca(2+) induces binding of the C2-domains to phospholipid membranes and to assembled SNARE-complexes; both actions contribute to triggering exocytosis (By similarity). SYT7 binds Ca(2+) with high affinity and slow kinetics compared to other synaptotagmins (By similarity). Involved in Ca(2+)-triggered lysosomal exocytosis, a major component of the plasma membrane repair. Ca(2+)-regulated delivery of lysosomal membranes to the cell surface is also involved in the phagocytic uptake of particles by macrophages (By similarity). Ca(2+)-triggered lysosomal exocytosis also plays a role in bone remodeling by regulating secretory pathways in osteoclasts and osteoblasts (By similarity). In case of infection, involved in participates cell invasion by Trypanosoma cruzi via Ca(2+)- triggered lysosomal exocytosis. Involved in cholesterol transport from lysosome to peroxisome by promoting membrane contacts between lysosomes and peroxisomes: probably acts by promoting vesicle fusion by binding phosphatidylinositol-4,5-bisphosphate on peroxisomal membranes (By similarity). Acts as a key mediator of synaptic facilitation, a process also named short-term synaptic potentiation: synaptic facilitation takes place at synapses with a low initial release probability and is caused by influx of Ca(2+) into the axon terminal after spike generation, increasing the release probability of neurotransmitters (By similarity). Probably mediates synaptic facilitation by directly increasing the probability of release (By similarity). May also contribute to synaptic facilitation by regulating synaptic vesicle replenishment, a process required to ensure that synaptic vesicles are ready for the arrival of the next action potential: SYT7 is required for synaptic vesicle replenishment by acting as a sensor for Ca(2+) and by forming a complex with calmodulin (By similarity). Also acts as a regulator of Ca(2+)- dependent insulin and glucagon secretion in beta-cells (By similarity). Triggers exocytosis by promoting fusion pore opening and fusion pore expansion in chromaffin cells (By similarity). Also regulates the secretion of some non-synaptic secretory granules of specialized cells (By similarity).
Synonyms: SytVII; PCANAP7; IPCA-7; SYT-VII; MGC150517; IPCA7
Tractability: Antibody: UniProt places it where antibodies can reach, with medium confidence; UniProt predicts a signal peptide or a membrane-spanning region; its Gene Ontology location is reachable by antibodies, with medium confidence. PROTAC: ubiquitination databases record sites on it; its protein half-life has been measured.
Gene: Protein-coding gene on chromosome 11 (61,513,714 to 61,581,167, reverse strand). Ensembl gene ENSG00000011347.
Subcellular location: Cell membrane; Presynaptic cell membrane; Cytoplasmic vesicle, secretory vesicle, synaptic vesicle membrane; Lysosome membrane; Cytoplasmic vesicle, phagosome membrane; Peroxisome membrane; Cytoplasmic vesicle, secretory vesicle membrane
Pathways (Reactome):
Neuronal System: Neurexins and neuroligins
Gene Ontology:
Molecular function: protein binding; calcium ion sensor activity; calcium-dependent phospholipid binding; calmodulin binding; phosphatidylinositol-4,5-bisphosphate binding; SNARE binding; calcium ion binding; clathrin binding
Biological process: calcium ion regulated lysosome exocytosis; calcium ion-regulated exocytosis of neurotransmitter; calcium-dependent activation of synaptic vesicle fusion; phagocytosis; phagosome-lysosome fusion; plasma membrane repair; regulation of bone remodeling; regulation of calcium ion-dependent exocytosis; regulation of glucagon secretion; regulation of insulin secretion; regulation of phagocytosis; short-term synaptic potentiation; synaptic vesicle recycling; vesicle fusion; vesicle-mediated cholesterol transport; vesicle-mediated transport; calcium-ion regulated exocytosis; positive regulation of calcium ion-dependent exocytosis; positive regulation of transport; regulation of endocytosis; regulation of synaptic vesicle endocytosis
Cellular component: extracellular exosome; axon; early phagosome; lysosomal membrane; lysosome; peroxisomal membrane; peroxisome; plasma membrane; presynaptic membrane; synapse; synaptic vesicle; cytosol; dense core granule; endomembrane system; hippocampal mossy fiber to CA3 synapse; membrane; phagocytic vesicle membrane; secretory vesicle; synaptic vesicle membrane; transport vesicle membrane
Genetic constraint (gnomAD): Loss-of-function variants: 29 observed, 71.55 expected, observed/expected ratio (o/e) 0.41, 90% interval 0.3 to 0.55. The upper end of that interval is the gene's LOEUF score, 0.55, which puts it in group 2 of 6, group 1 being the genes least tolerant of losing a copy. Missense variants: 693 observed, 948.21 expected, observed/expected ratio (o/e) 0.73, 90% interval 0.69 to 0.78. Synonymous variants: 376 observed, 396.56 expected, observed/expected ratio (o/e) 0.95, 90% interval 0.87 to 1.03.
Homologues: Orthologues: chimpanzee SYT7 (99% identical), pig SYT7 (99% identical), dog SYT7 (98% identical), rat Syt7 (98% identical), mouse Syt7 (98% identical), macaque SYT7 (96% identical), guinea pig SYT7 (78% identical), tropical clawed frog syt7 (78% identical), rabbit SYT7 (74% identical), zebrafish syt7a (62% identical), zebrafish syt7b (53% identical), Drosophila melanogaster Syt7 (28% identical), and 1 more. Paralogues in human: SYT11 (24% identical), SYT4 (22% identical), SYT6 (22% identical), SYT2 (22% identical), SYT3 (22% identical), SYT9 (22% identical), SYT1 (21% identical), SYT10 (21% identical), SYT5 (20% identical), SYT17 (19% identical), RPH3A (18% identical), SYTL2 (17% identical), and 19 more.
Diseases named in the same sentence as SYT7 in open-access papers:
SYT7 is named in the same sentence as 50 diseases in open-access papers, as found by Europe PMC text mining. Sharing a sentence is not in itself a finding about the gene and the disease. The quoted sentences say what the papers report.
depression (6 papers, 2021 to 2025). "Furthermore, pancreatic insulin secretion and neuronal activity showed opposite diurnal patterns, in which the Syt7-deficiency-induced disequilibrium induced periodic antagonistic shifts in the mania- and depression-like behaviors." (PMID 40330888, 2025). "Importantly, these variants also uncoupled the function of syt7 in PPF versus synaptic depression, revealing a functional switch that is subordinate to alternative splicing." (PMID 41278746, 2025). "Instead, Syt7-mediated release offsets the underlying short-term depression." (PMID 38262726, 2024). "Interestingly, loss of syt7 caused more severe synaptic depression than EGTA-AM." (PMID 38536730, 2024). "Synaptotagmin-7 (Syt7) KO mice show diurnal fluctuations of mania- and depression-like behavioral abnormalities." (PMID 40330888, 2025). "Disruptions of SYT7 have been suggested as a risk factor for bipolar disorder (BD) in humans, with mutant Syt7 mice displaying manic and depression like behaviors." (PMID 33619613, 2021). "In summary, under similar expression levels of the three syt7 splice variants in cultured neurons, only the β splice variant rescues both the PPF and depression phenotypes in the KO, while all three variants rescue PPF (albeit via somewhat different mechanisms)." (PMID 41278746, 2025). "Although GluN2B-NMDAR hypoactivity has been shown to be involved in the induction of mania-like behaviors of the Syt7 KO mice in the dark phase, the reasons for the depression-like behaviors in the light phase and behavioral fluctuation remain unknown." (PMID 40330888, 2025). "Moreover, because SYT7 functions to promote docking of SVs during activity, to potentially regulate PPF, depression, and asynchronous release, there are likely to be numerous behavioral and coordination abnormalities that have yet to be described." (PMID 34543184, 2021).
gastric cancer (6 papers, 2019 to 2024). A primary or metastatic malignant neoplasm involving the stomach. "Synaptotagmin VII (SYT7) may also become a therapeutic target since it was found to be significantly associated with hepatic metastasis, recurrence, and poor prognosis in primary gastric cancer tissues." (PMID 38596287, 2024). "Surprisingly, recent studies have reported that SYT7 is highly expressed in cancers such as gastric cancer and osteosarcoma, and promotes cell proliferation and migration." (PMID 39235072, 2024). "Previous studies have shown that SYT7 can promote the progression and liver metastasis formation of gastric cancer." (PMID 37280656, 2023). "Previous studies showed that SYT7 played a significant role in the proliferation, migration, apoptosis, and cell cycle in multiple solid tumors, such as colorectal cancer, gastric cancer, non-small cell lung cancer, renal cell carcinoma, glioblastoma, and melanoma." (PMID 34930262, 2021). "In gastric cancer, SYT7 has been demonstrated to act as a driver for metastasis formation." (PMID 30647108, 2019). "SYT7 was demonstrated to play an essential role in non-small cell lung carcinoma, head and neck squamous cell carcinoma (HNSCC), gastric cancer, and CRC." (PMID 37958455, 2023). "Although we did not test the effect of SYT7 on the motility of lung cancer cells, SYT7 has been recognized as the driver for the metastasization of gastric cancer." (PMID 30647108, 2019).
bipolar disorder (5 papers, 2021 to 2024). A disorder of the brain that causes unusual shifts in mood, energy, activity levels and the ability to carry out day-to-day tasks. "Synaptotagmin-7 (Syt7) variants are associated with susceptibility to bipolar disorder; this study shows that Syt7 acts as a calcium sensor to drive spontaneous glutamate release which uniquely activates postsynaptic GluN2B-containing glutamate receptors." (PMID 34228711, 2021). "Recently, we have found that Syt7 is a susceptible gene for bipolar disorder (BD) and that its deficits could induce bipolar-like behaviors in mice." (PMID 34228711, 2021). "Mice with silenced genes, including SYT7 in the hippocampus, showed manic-like and depressive-like behavioral fluctuations, which were analogous to the mood cycling symptoms of bipolar disorder, suggesting that SYT7 may be a candidate risk factor for behavioral abnormalities." (PMID 38397218, 2024). "Interestingly, this function of Syt7 is disrupted in bipolar disorder susceptibility variants." (PMID 34228711, 2021). "In the plasma samples of bipolar disorder (BD) patients, the Syt7 mRNA level was significantly reduced, and in Syt7 knockout mice, mood cycling symptoms of BD was observed." (PMID 36129576, 2022). "Finally, Syt7 SNPs identified in bipolar disorder patients destroy the function of Syt7 in spontaneous release in patient iPSC-derived and mouse hippocampal neurons." (PMID 34228711, 2021). "Indeed, a recent report described bipolar disorder symptoms in SYT7KO mice, as well as decreased SYT7 mRNA in the plasma samples of human patients with bipolar disorders." (PMID 34543184, 2021).
lung carcinoma (5 papers, 2019 to 2024). "The lung transcriptomic data of EMR mice show changes in the expression of genes previously identified in lung cancer cells, including metastasis associated in lung denocarcinoma transcript 1 (Malat1), synaptotagmin 7 (Syt7), and tubulin beta 3 class III (Tubb3)." (PMID 35619714, 2022). "Consistent with these previous studies, SYT7 was highly expressed in lung cancer in the TCGA database." (PMID 39235072, 2024). "Another study demonstrated that the expression levels of SYT7 were elevated in both lung cancer tissues and cell lines." (PMID 36004367, 2022). "SYT7 is overexpressed in lung cancer as well as in colorectal cancer and glioma, which promotes cell proliferation, inhibits cell apoptosis, and results in unfavorable prognosis." (PMID 34229539, 2021). "In the present study, we have shown that synaptotagmin-7 (SYT7) expression was up-regulated in lung cancer." (PMID 30647108, 2019). "Having shown that SYT7 inhibited the senescence of lung cancer cells, we next explored the molecular mechanism." (PMID 30647108, 2019). "Taken together, these data suggested that SYT7 promoted the malignant behavior of lung cancer cells." (PMID 30647108, 2019). "One of the most interesting findings of the present study was that SYT7 inhibited the senescence of lung cancer cells." (PMID 30647108, 2019). "Using an open-access database, we searched for genes important for lung tumorigenesis and identified an association between higher SYT7 expression and worse survival, suggesting the important function of SYT7 in lung cancer." (PMID 30647108, 2019). "To examine the functions of SYT7 in lung cancer, we forced the expression of SYT7 in A549 and H23 cells." (PMID 30647108, 2019). "We next assessed the expression of SYT7 in lung cancer tissues and paired adjacent normal tissues by using immunohistochemistry (IxHC) and Western blot analysis." (PMID 30647108, 2019). "SYT7 also promoted the growth and colony formation of lung cancer cells and inhibited their senescence." (PMID 30647108, 2019). "Overexpression of SYT7 in lung cancer cells promoted the growth of A549 and H23 cells, not only in liquid cultures but also in soft agar." (PMID 30647108, 2019). "In addition, SYT7 was shown to inhibit senescence and promote growth and colony-forming capacity in lung cancer cells." (PMID 36004367, 2022). "SYT7 was shown to promote the growth and colony formation of lung cancer cells." (PMID 30647108, 2019). "In addition, using a series of lung cancer cell lines (A549, H23, H520, SPAC-A-1) and normal lung cells (Bease-2B), we found higher expression level of SYT7 protein in lung cancer cell lines." (PMID 30647108, 2019). "We first turned to the GEPIA database to explore the expression pattern of SYT7 in lung cancer." (PMID 30647108, 2019). "Taken together, the present study demonstrates the oncogenic roles of SYT7 in lung cancer, and suggests that SYT7 may be a good therapeutic target for lung cancer treatment." (PMID 30647108, 2019). "We found that SYT7 protein levels in lung cancer tissues were elevated." (PMID 30647108, 2019). "Taken together, the present study revealed the oncogenic role of SYT7 in lung cancer and suggested that SYT7 might be a good therapeutic target for lung cancer treatment." (PMID 30647108, 2019). "Having shown the effects of SYT7 overexpression on the growth and senescence of lung cancer cells, we aimed to explore the functions of endogenous SYT7 by knocking down its expression in lung cancer cells." (PMID 30647108, 2019). "However, the function of SYT7 in lung cancer remains unknown." (PMID 30647108, 2019). "In summary, SYT7 may serve as an oncogene in GC, CRC, HCC, lung cancer, glioblastoma, osteosarcoma, and HNSCC." (PMID 36004367, 2022).
non-small cell lung carcinoma (4 papers, 2021 to 2023). A group of at least three distinct histological types of lung cancer, including non-small cell squamous cell carcinoma, adenocarcinoma, and large cell carcinoma. "SYT7 has also been reported to promote the proliferation, invasion, metastasis, and the inhibition of cell apoptosis of non-small cell lung cancer cells." (PMID 37280656, 2023). "One recent study showed that SYT7 was upregulated in non-small-cell lung cancer (NSCLC), and its high expression was positively correlated with T stage and tumor differentiation." (PMID 36004367, 2022). "In non-small cell lung cancer, the expression of SYT7 was distinctly higher than that of para-carcinoma tissues, and the high expression of SYT7 protein was related to the low survival rate of patients." (PMID 34930262, 2021).
colorectal cancer (3 papers, 2019 to 2021). A primary or metastatic malignant neoplasm that affects the colon or rectum. "Moreover, compared with normal tissues, the levels of SYT7 in colorectal cancer tissues were up-regulated and were positively correlated with pathological staging." (PMID 34930262, 2021).
Hypertension (3 papers, 2021 to 2026). The presence of chronic increased pressure in the systemic arterial system. "In humans, the methylation level of SYT7 has been significantly associated with hypertension." (PMID 40805107, 2025). "Methylation levels of PRDM6 and SYT7 were significantly associated with hypertension." (PMID 35087571, 2021). "We found that DNA methylations in the promoters of PRDM6, HDAC9, IGFBP3, SYT7, TBX2 and C17orf82 were significantly associated with BP or hypertension in the Chinese Han population." (PMID 35087571, 2021). "In summary, the present study showed that DNA methylation in the promoters of PRDM6, HDAC9, IGFBP3, LRRC10B, SYT7, PDE3A, TBX2 and C17orf82 genes were significantly associated with BP or hypertension." (PMID 35087571, 2021).
Alzheimer disease (2 papers, 2020 to 2021). A progressive, neurodegenerative disease characterized by loss of function and death of nerve cells in several areas of the brain leading to loss of cognitive function such as memory and language. "Surprisingly, we discovered that the amino-terminus of SYT7 is cleaved by the Alzheimer’s disease-relevant γ-secretase complex; the stability and localization of SYT7 is dependent on this proteolytic processing step and concurrent palmitoylation." (PMID 34543184, 2021). "Indeed, mammalian SYT7 levels are post-transcriptionally modulated by γ-secretase proteolytic activity and APP, linking it to SV trafficking defects in Alzheimer’s disease." (PMID 32343229, 2020).
cardiac hypertrophy (2 papers, 2025 to 2026). "Loss-of-function of Syt7 preserves cardiac function and attenuates stress-induced arrhythmias, myocardial hypertrophy, and fibrosis." (PMID 41424848, 2026). "Inhibition of Syt7 reduced myocardial hypertrophy, as evidenced by reduced heart volume, decreased ratio of HW/BW and HW/TL, and smaller cardiomyocyte cross-sectional areas." (PMID 41424848, 2026). "Both genetic knockout and cardiomyocyte-specific knockdown of Syt7 significantly preserved cardiac function and rhythm, and alleviated myocardial hypertrophy and fibrosis in CORT-treated mice." (PMID 41424848, 2026). "Our group recently reported that synaptotagmin-7 was expressed in mice ventricular myocytes and mediated cardiac hypertrophy by targeting autophagy." (PMID 40279007, 2025).
epilepsy (2 papers, 2023 to 2026). A brain disorder characterized by episodes of abnormally increased neuronal discharge resulting in transient episodes of sensory or motor neurological dysfunction, or psychic dysfunction. "Some of them were already known to play a role in AD: PICK1 is involved in synaptic scaling; AP2A2 is involved in receptor-mediated endocytosis; SYT7 is regulated by amyloid precursor protein; and KIF5B is critical for GABAAR transport, and its deletion causes epilepsy." (PMID 36538112, 2023).
glioblastoma (2 papers, 2019 to 2022). The most malignant astrocytic tumor (WHO grade IV). "Downregulation of SYT7 can promote cellular apoptosis and subsequently inhibit the growth of glioblastoma." (PMID 36004367, 2022). "SYT7 promoted the proliferation of colon cancer cells and glioblastoma cells." (PMID 30647108, 2019).
mental disorder (2 papers, 2021 to 2022). A disease that has its basis in the disruption of mental process. "Here, we show that Syt7 is a redundant Ca2+ sensor with Syt1/Doc2 to drive spontaneous glutamate release, which functions uniquely to activate the postsynaptic GluN2B-containing NMDARs that significantly contribute to mental illness." (PMID 34228711, 2021).